TERT (telomerase reverse transcriptase)
Diseases named in the same sentence as TERT in open-access papers (continued):
Sharing a sentence is not in itself a finding about the gene and the disease.
thyroid (27 papers, 2016 to 2025). "Our case further reinforces the significance of TERT‐p mutation in the poor differentiation/presence of STc and metastatic capability during thyroid tumorigenesis." (PMID 41090246, 2025). "TERT: Activating mutations in the promoter of the telomerase reverse transcriptase (TERT) are mostly a late event in thyroid tumorigenesis." (PMID 31540307, 2019). "At the time of last follow up, five patients died of thyroid disease: four in the TERT+BRAF mutation group and one in the BRAF mutation alone group." (PMID 29312581, 2017). "Although not routinely done in clinical settings, molecular evaluation for BRAFV600E or TERT mutation may complement the prognostic strength of other clinical and histological features in thyroid risk stratification." (PMID 41174793, 2025). "Indeed, studies have shown that RAS with TERT promoter co-mutation may play a synergistic role in thyroid tumorigenesis and increase aggressiveness behavior and poor prognosis." (PMID 40940948, 2025). "The TERT locus is a critical vulnerability site for tumor progression, dedifferentiation, and aggressiveness in thyroid carcinogenesis." (PMID 40272676, 2025). "Thyroid nodules with both RAS and TERT mutations were significantly larger, had higher RAS AF, and showed a strong correlation with positive GEP results compared to nodules with RAS mutations alone." (PMID 40940948, 2025). "Several types of genetic mutations, such as those present in BRAF, RAS, RET, TERT-promoter (TERT-p), and CTNNB, are involved in thyroid carcinogenesis." (PMID 35892838, 2022). "Among the genetic alterations, the diagnostic and prognostic value of BRAFV600E mutation and TERT promoter mutations have been well studied in PTC and other thyroid malignancies." (PMID 35207709, 2022). "We caution against the assumption of mechanisms identified in other cancer lineages being identical in TERT-mutant thyroid specimens." (PMID 35053525, 2022). "These are known to harbor the highest frequencies of TERT alterations among thyroid lesions." (PMID 38616265, 2024). "Therefore, to obtain good quality data from a limited number of TERT-positive cases, the two pathologists who are experienced in thyroid pathology that were involved in our study conducted fine-grained TERT ROI annotation in tumor areas." (PMID 36984536, 2023). "In benign tumours, TERT mRNA expression was found in 17% of the follicular thyroid adenoma (FTA) with increased levels of expression in smaller tumours and associated with the presence of thyroiditis." (PMID 32659948, 2020). "However, in benign tumours, TERT mRNA expression can be misinterpreted by the presence of lymphocytic infiltration and thyroiditis." (PMID 32659948, 2020). "The tumors were sequenced for mutations in the TERT promoter and 22 additional cancer-related genes, interestingly; one patient was shown to carry a deleterious intronic variant in PTEN, a tumor suppressor gene coupled to thyroid tumorigenesis and Cowden syndrome." (PMID 31699114, 2019). "Some of the previous studies concur in considering TERT amplification, like TPM, as a late event in thyroid carcinogenesis, more common in advanced tumor stages." (PMID 40272676, 2025). "As our multivariate analysis revealed, only a subset of genes—specifically TERT and BRAF—along with clinical factors (T stage and unilateral thyroid involvement) were independently predictive of lung metastasis." (PMID 41306438, 2025). "Other features such as gender, multifocality, thyroiditis, presence of thyroid nodules, and mutation status of KRAS, BRAF, and TERT did not significantly differ between the high- and low-risk groups in this validation set." (PMID 40650680, 2025).
thyroid (continued). "Likewise, none of the reported studies, involving PTCs, has investigated the relationship between TERT amplification or TERT amplification + TPM and clinical-pathological parameters of poor outcome in thyroid patients." (PMID 40272676, 2025). "While our sample included four tumors with thyroiditis, there does not appear to be a significant influence on TERT levels from lymphocytes, using a ddPCR cutoff threshold of 10%." (PMID 34702207, 2021).
osteosarcoma (26 papers, 2012 to 2025). A usually aggressive malignant bone-forming mesenchymal neoplasm, predominantly affecting adolescents and young adults. "In contrast to osteosarcomas, malignant H3.3‐mutated tumours were enriched for a variety of alterations involving TERT, other than amplification, suggesting telomere dysfunction in the transformation of benign to malignant GCTB." (PMID 32866294, 2020). "Notwithstanding, it was also reported that TERT mRNA expression and telomerase activity were associated with unfavorable outcome in osteosarcoma, although TERT was the stronger of the two prognostic markers." (PMID 32290440, 2020). "Clinical osteosarcomas with high expression of TERT exhibited more significant malignant characteristics than others, as evidenced by their higher proliferation efficiency." (PMID 40688111, 2025). "TERT was highly expressed in cisplatin-resistant osteosarcoma cells, where it shuttles from the nucleus to the mitochondrion in response to cisplatin therapy, thereby suppressing cisplatin-induced apoptosis in osteosarcoma cells." (PMID 39980969, 2024). "Wei and colleagues created a unique approach for detecting simultaneous TA and TERT levels in osteosarcomas using an ingeniously designed stem-loop probe and CRISPR-Cas12a." (PMID 35328421, 2022). "TERT-induced miR-500a upregulation increased tumor aggressiveness in osteosarcoma cell lines, and WNT/β-catenin is predicted to be one of the affected downstream signaling pathways." (PMID 34439356, 2021). "Using immunofluorescence imaging, we assayed the localization of ATRX and DAXX in G292 and the TERT + osteosarcoma line SJSA1." (PMID 30872698, 2019). "Confocal fluorescence microscopy disclosed translocation of TERT from the nucleus to mitochondria in all three osteosarcoma cell lines examined, clearly confirming our theory." (PMID 28765565, 2017). "PML was stably silenced in U2OS osteosarcoma cells and TERT-immortalized normal human diploid fibroblasts (NHDF) using a previously well characterized short-hairpin RNA28 (shPML-A)." (PMID 28332630, 2017). "Our data clearly demonstrate that TERT significantly inhibits cisplatin-induced apoptosis in osteosarcoma cells in correlation with its mitochondrial translocation." (PMID 28765565, 2017). "Our results suggested that TERT reduces intracellular ROS levels, and further alleviated apoptosis by inhibiting mitochondrial apoptotic pathway in cisplatin-treated osteosarcoma cells." (PMID 28765565, 2017). "TERT mRNA expression was significantly higher in cisplatin-treated (5 μmol/L, 24 h) osteosarcoma cells, compared to untreated cells." (PMID 28765565, 2017). "In cisplatin-resistant osteosarcoma cells, TERT translocates to in mitochondria, alleviates cisplatin-induced ROS levels and inhibits the mitochondrial pathway of apoptosis, promoting cell survival." (PMID 28765565, 2017). "Our results suggest that constitutive TERT expression antagonizes cisplatin-induced apoptosis via regulation Bcl-2, Bcl-xl, Bax and caspase-3 in osteosarcoma cells." (PMID 28765565, 2017). "To comprehensively understand the chemoresistance effects of TERT, we initially investigated TERT expression patterns in osteosarcoma cells subjected to cisplatin treatment." (PMID 28765565, 2017). "Western-blot revealed significantly elevated TERT protein in osteosarcoma cells treated with cisplatin relative to untreated cells, consistent with mRNA data." (PMID 28765565, 2017). "Previously, our group showed higher telomerase reverse transcriptase(TERT) expression in cisplatin resistant osteosarcoma cells." (PMID 28765565, 2017). "Constitutive expression of TERT in osteosarcoma cells resulted in decreased level of intracellular ROS." (PMID 28765565, 2017). "In this study, confocal fluorescence microscopy experiments revealed that TERT translocates from the nucleus to mitochondria in cisplatin treated osteosarcoma cells." (PMID 28765565, 2017).
osteosarcoma (continued). "Based on findings that osteosarcoma spheres had increased TERT expression, we engineered osteosarcoma cell lines that stably express a human TERT promoter-driven GFP reporter." (PMID 27102300, 2016). "To test this, we stably transduced osteosarcoma cell lines with a lentiviral vector in which the human TERT promoter drives expression of green fluorescent protein (GFP)." (PMID 24334332, 2013). "It is reported that TERT promotes epithelial proliferation through Myc- and Wnt-related pathways, and the Wnt pathway has also been shown to be involved in osteosarcoma pathogenesis." (PMID 24334332, 2013). "In addition, all the experiments in vitro and in vivo validated that inhibiting TERT abundance reduces the proliferation, invasion, and migration capabilities of osteosarcoma cells." (PMID 40688111, 2025). "Moreover, the suppression of TERT expression decreased osteosarcoma cell metastasis, motility, and proliferation." (PMID 38431660, 2024). "Consequently, the technique would open up a new dimension for bioanalysis and disease diagnostics for osteosarcomas by combining three indicators in one detection, including TA and TERT levels." (PMID 35328421, 2022). "To determine whether TERT expression is altered after treatment with cisplatin, we initially analyzed TERT mRNA levels in osteosarcoma cell lines MG63, U2OS and 143B." (PMID 28765565, 2017). "To determine whether TERT plays a role in the mitochondrial pathway of apoptosis, we established stable TERT-overexpressing and -depleted osteosarcoma cell lines." (PMID 28765565, 2017). "Our findings suggest that inhibition of TERT may provide an effective therapeutic approach to eliminate cisplatin-dependent apoptosis in osteosarcoma cells, supporting its utility as a target for further clinical development." (PMID 28765565, 2017). "Accordingly, we hypothesized that increased expression of TERT in cisplatin treated osteosarcoma cells promotes its translocation from the nucleus to cytoplasm." (PMID 28765565, 2017). "Our finding that TERT shuttles from the nucleus to the mitochondrion in response to cisplatin treatment and inhibits cisplatin-induced apoptosis in osteosarcoma cells may be especially important to overcome drug resistance." (PMID 28765565, 2017). "This study provides a novel insight into the mechanism whereby TERT suppresses cisplatin-induced apoptosis and may open a new way to solving osteosarcoma chemo-resistance." (PMID 28765565, 2017). "We hypothesized that translocated TERT promotes resistance of osteosarcoma cells to cisplatin-induced intracellular ROS production." (PMID 28765565, 2017). "Moreover, TERT suppressed cisplatin-induced apoptosis and improved mitochondrial function via alleviating intracellular ROS in osteosarcoma cells." (PMID 28765565, 2017). "Data from the current study provides strong evidence that constitutive TERT expression leads to not only reduced intracellular ROS levels, but also significant inhibition of the mitochondrial pathway of apoptosis induced by cisplatin, promoting resistance of osteosarcoma cells to cisplatin therapy." (PMID 28765565, 2017). "However, TERT was strongly expressed at both mRNA and protein levels in all three osteosarcoma cells treated with 5 μmol/L cisplatin for 24 h in keeping with our previous in vitro finding of TERT enrichment in chemo-resistant osteosarcoma cells." (PMID 28765565, 2017). "Accordingly, in osteosarcoma, TUBB and MAP3K5 were believed to function as tumor suppressors, actively inhibiting tumor growth and progression, while TERT and PPARG appear to act as cancer promoters, exacerbating the development of osteosarcoma." (PMID 39980969, 2024). "Our results showed that compared with osteoblasts, CPEB3, EIF4E3, RBM34, RPS27L, RPS29 and TDRD6 were down-regulated in U2OS and 143B, while NXT2, TERT, TLR8 and ZC3HAV1 were up-regulated in osteosarcoma cells." (PMID 34926575, 2021).
osteosarcoma (continued). "A risk score model constructed based on four epigenetic modification-related genes (MYC, TERT, EIF4E3, and RBM34) can effectively predict the prognosis of patients with osteosarcoma." (PMID 34853590, 2021). "While apoptosis of TERT-siRNA transfected cells was significantly increased, compared to that in control MG63 osteosarcoma cells." (PMID 28765565, 2017). "We designed a system to achieve specific expression of CRISPR-dCas9-KRAB in osteosarcoma cells by using the creatine kinase muscle (CKM) promoter to drive dCas9-KRAB and the telomerase reverse transcriptase (TERT) promoter to drive single guide (sg)RNA expression." (PMID 37415116, 2023). "On the other hand, none of the tested compounds induced DSBs in TERT-negative normal bronchial epithelial cells or ALT-positive osteosarcoma cells, suggesting that the induction of DSBs is dependent on telomerase inhibition." (PMID 36437244, 2022). "In our study, TERT significantly inhibited caspase-3 activity in osteosarcoma cells, but exerted no obvious effects on caspase-9 activity (data not shown)." (PMID 28765565, 2017). "The co-amplification of TERT and RICTOR was only seen in osteosarcoma." (PMID 28643781, 2017). "In the literature, a gain of 5p has been found in osteosarcoma and malignant fibrous histiocytoma, and studies combining aCGH and gene expression assays suggest that 5pter-p15.3 harbors several candidate oncogenes including TRIP13, TERT, NDUFS6, and ADAMT16." (PMID 22551002, 2012). "Unlike other cancers, osteosarcoma has a higher prevalence of ALT in relation to TERT." (PMID 35887382, 2022). "To test the interaction of TERC with HuR in cells, we employed human osteosarcoma U2OS cells, which do not express endogenous human TERT (hTERT) or TERC30." (PMID 29880812, 2018). "On the other hand, TXT2 and TXT4 failed to induce DNA damage in the ALT-positive osteosarcoma U2OS cells, which in turn were characterized by a remarkable accumulation of γ-H2AX upon exposure to MTX, whereas equitoxic amounts of all compounds failed to elicit DNA damage in TERT-negative NHBE cells." (PMID 36437244, 2022).
diffuse astrocytoma (25 papers, 2018 to 2024). A low-grade (WHO grade II) astrocytic neoplasm. "TERT promoter mutations have emerged as denominators of specific subgroups among diffuse astrocytomas with a higher propensity to recur as high-grade tumors and allow for the classification of otherwise WHO grade II diffuse astrocytoma as WHO grade IV." (PMID 33755803, 2021). "Among IDH-wild-type grade II diffuse astrocytomas, the TERT promoter mutation was the most common mutation found in the brain (67%, 4/6) compared to BRAF p.V600E (14%, 2/14) mutation in the spine (Fisher test: p = 0.037)." (PMID 32771057, 2020). "However, only one case of the IDH wildtype diffuse astrocytoma with TERT promoter mutation and + 7/ − 10 copy number changes was included in our study due to a lack of routine molecular testing in our institution." (PMID 38305926, 2024). "Interestingly, some of the IDH-wildtype diffuse astrocytomas demonstrated hotspot mutations in the TERT promoter (4 mutations out of 9 tumors: 44.4%)." (PMID 29693015, 2018). "A group of 157 patients, classified as WHO grade 3 anaplastic astrocytoma (78.3%) and WHO grade 2 diffuse astrocytoma (21.7%), participated in a multicenter study to explore the impact of EGFR amplification and TERT-promotor mutation on overall survival (OS)." (PMID 38539537, 2024). "However, since 2022, the new WHO classification has added more genetic mutations that classify diffuse astrocytoma as grade IV gliomas (homozygous CDKN2A/B deletion, TERT promoter mutation, EGFR gene amplification, and chromosome 7 gain/chromosome 10 loss)." (PMID 37534252, 2023). "Furthermore, there is one case of diffuse astrocytoma with IDH wild-type status and TERT mutation included in this study." (PMID 33963441, 2021).